METTL3 (methyltransferase 3, N6-adenosine-methyltransferase complex catalytic subunit)
Diseases named in the same sentence as METTL3 in open-access papers (continued):
Sharing a sentence is not in itself a finding about the gene and the disease.
pancreatic cancer (continued). "In short, smoking plays a role in the development and progression of pancreatic cancer through the METTL3/miR-25-3p/PHLPP2/AKT regulatory axis." (PMID 35155557, 2022). "METTL3 influences the sensitivity of pancreatic cancer cells to anticancer reagents via a ubiquitin-dependent process, RNA splicing and the regulation of cellular processes." (PMID 35155557, 2022). "In pancreatic cancer, METTL3 was overexpressed as a result of cigarette smoke condensate induced hypomethylation of the METTL3 promoter." (PMID 36429032, 2022). "Conversely, METTL3 knockdown promoted pancreatic cancer cell proliferation, invasion, and migration in vitro." (PMID 36008936, 2022). "This means that METTL3 is probably a potential target for increasing therapeutic effect in patients with pancreatic cancer." (PMID 36008936, 2022). "For example, METTL3 promoted resistance to radiotherapy and reduced survival in pancreatic cancer patients, while FTO was expressed at significantly higher levels in CSCC tissues than in pre-cancerous tissues." (PMID 34660577, 2021). "In previous study, Taketo et.al showed that METTL3 knockdown sensitized pancreatic cancer to multiple anti-cancer reagents, including gemcitabine, 5-fluorouracil, cisplatin and irradiation as well." (PMID 33596916, 2021). "METTL3 and METTL14 in the m6A methyltransferase component are expected to become new targets for tumor radiotherapy and chemotherapy sensitization, and METTL3 can promote the chemotherapy and radiotherapy sensitivity of pancreatic cancer cells." (PMID 33741902, 2021). "The knockdown of methyltransferase-like 3 (METTL3) in pancreatic cancer greatly improved sensitivity to drugs such as 5-fluorouracil, cisplatin, gemcitabine, and irradiation." (PMID 34822387, 2021). "METTL3 was reported to promote cancer progression and increase chemo, radio, and chemoradio-sensitivity in pancreatic cancer." (PMID 34458141, 2021). "In support of this, METTL3 knockout in pancreatic cancer cells increased sensitivity to gemcitabine, 5′-fluorouracil and cisplatin." (PMID 33855021, 2021). "m6A RNA modifications also play an essential role in pancreatic cancer, with METTL3 promoting chemo- and radiation resistance in pancreatic cancer cells." (PMID 34660577, 2021). "METTL3 increases m6A modification in pancreatic cells, and METTL3 can promote the proliferation and invasion of pancreatic cancer cells." (PMID 34246319, 2021). "Taken together, our study revealed crucial functions of NUCB1 in suppressing proliferation and enhancing the effects of gemcitabine in pancreatic cancer cells and identified METTL3-mediated m6A modification as a mechanism for NUCB1 downregulation in PDAC." (PMID 33855021, 2021). "METTL3 is known to promote the resistance of pancreatic cancer cells against chemotherapy and radiotherapy." (PMID 33072775, 2020). "It was suggested that a high level of METTL3 expression was associated with a high pathological stage in PDAC, as well as chemo- and radio-resistance in pancreatic cancer cells." (PMID 32854717, 2020). "METTL3-depleted pancreatic cancer cells display a decreased ability of cell proliferation and invasion, and an increased sensitivity to the treatment of anticancer reagents and irradiation." (PMID 33372610, 2020). "Recent studies reported that METTL3 accelerated the maturation of pri-miR221/22220 and pri-miR-2521 in bladder and pancreatic cancers." (PMID 33037176, 2020). "Knockdown of METTL3 can significantly increase the sensitivity of pancreatic cancer cells to 5-fluorouracil (5-FU), cisplatin, gemcitabine, and radiotherapy." (PMID 33072775, 2020). "The expression of METTL3 increases at both protein and mRNA levels in pancreatic cancer; METTL3 knockdown inhibits cell proliferation, invasion and migration." (PMID 33029866, 2020). "In pancreatic cancer, m6A and METTL3 are enriched in tumor specimens, and METTL3 boosts cancer cell proliferation, invasion, and migration via m6A modification." (PMID 32709063, 2020).
pancreatic cancer (continued). "In pancreatic cancer, it was reported that METTL3 promotes cancer progression and chemo- and radio-resistance." (PMID 32843065, 2020). "In the present study, we showed that knockdown of Mettl3 can restore the chemosensitivity of HepG2/ADR cells, which is consistent with recent study that Mettl3 can promote the chemo- and radioresistance of pancreatic cancer cells." (PMID 32206097, 2020). "METTL3 was found to increase the sensitivity of cells to anticancer reagents such as gemcitabine, 5‐fluorouracil, cisplatin and irradiation in pancreatic cancer, indicating the potential role of METTL3 in chemo‐ and radiotherapy resistance." (PMID 32808488, 2020). "Gemcitabine has emerged as an inducer of apoptosis in pancreatic cancer cells with low METTL3 expression." (PMID 33029866, 2020). "METTL3 is an effective therapeutic target for several cancers, such as pancreatic cancer, melanoma and lung adenocarcinoma." (PMID 31808521, 2019). "Taketo and coworkers established METTL3-knockdown pancreatic cancer cell line by using short hairpin RNA." (PMID 31810483, 2019). "For instance, METTL3 depletion sensitizes pancreatic cancer cells to anticancer agents such as gemcitabine, 5-fluorouracil, cisplatin, and irradiation." (PMID 31921664, 2019). "A sphere formation assay revealed that pancreatic cancer cells with METTL3 knockdown showed significantly lower self-renewal abilities than control cells." (PMID 30149601, 2018). "Moreover, studies have demonstrated that silencing Mettl3 sensitizes pancreatic cancer cells to chemotherapy." (PMID 41517663, 2026). "Furthermore, METTL16 and METTL3 are recognized as pivotal m6A modulators correlated with favorable prognosis in pancreatic cancer patients." (PMID 40986143, 2025). "Moreover, CD8 + T cells, which play an important role in antitumor immunity, were reduced in the infiltration of pancreatic cancer cells that underwent local invasion, high METTL3 and high EMP1 expression." (PMID 41285728, 2025). "lncRNA LIFR‐AS1 is stabilized by m6A modification by METTL3 and promotes pancreatic cancer growth." (PMID 40448344, 2025). "However, there is currently few research confirming that METTL3 or TRIM21 regulates the ferroptosis process in pancreatic cancer." (PMID 40175350, 2025). "METTL3 affects pancreatic cancer progression by promoting degradation of HMGB1." (PMID 40495163, 2025). "Here, we demonstrate that the cellular protein METTL3, which was previously shown to promote pancreatic cancer cell proliferation, invasion, and resistance to chemotherapy, plays a positive role in oncolytic virus replication in most of the tested human pancreatic cancer cell lines." (PMID 40214229, 2025). "Specifically, METTL16 and METTL3 have distinct prognostic implications in pancreatic cancer." (PMID 40986143, 2025). "Consistently, METTL3 expression was significantly elevated in pancreatic cancer tissues." (PMID 40175350, 2025). "However, the precise mechanisms by which METTL3 functions as an oncogene in pancreatic cancer and the upstream regulation of METTL3 degradation are largely require further investigation." (PMID 40175350, 2025). "Our study elucidated the precise molecular mechanism of the TRIM21-METTL3 axis in pancreatic cancer and revealed that METTL3 may be a potential target in pancreatic cancer therapy." (PMID 40175350, 2025). "Pancreatic cancer is highly lethal, and METTL3 plays a crucial role in the regulation of m6A." (PMID 40495163, 2025). "To understand the functional consequences of this interaction, we first examined whether the expression of TRIM21 affects the METTL3 protein levels in pancreatic cancer cells." (PMID 40175350, 2025). "Similarly, in oral squamous cell carcinoma and pancreatic cancer, METTL3-catalyzed m6A installation on specific mRNAs such as BMI1 or E2F family transcripts leads to their increased translation and confers invasive, stem-like traits to tumor cells." (PMID 41301491, 2025).
pancreatic cancer (continued). "Notably, we found that celastrol treatment mediated the reduction of m6A levels of Claspin and Bcl-2 mRNA by downregulating METTL3, leading to the degradation of Claspin and Bcl-2 mRNA in pancreatic cancer cells." (PMID 38110764, 2023). "METTL3 increased the expression of PD-L1 via lncRNA MALAT1 in pancreatic cancer cells." (PMID 36835633, 2023). "Thus, targeting methyltransferases such as METTL3 or their target transcripts seems to be a promising approach for pancreatic cancer therapeutics, and there have been evidence supporting it." (PMID 36977668, 2023). "Based on these data, it can be concluded that celastrol treatment decreased the global RNA m6A modification, especially reduced the mRNA m6A modification of Claspin and Bcl-2 probably by downregulating METTL3, leading to the downregulation of Claspin and Bcl-2 in pancreatic cancer cells." (PMID 38110764, 2023). "Moreover, our results indicated that celastrol treatment downregulated METTL3 and decreased m6A levels of Claspin and Bcl-2 mRNA, leading to the degradation of Claspin and Bcl-2 mRNA in pancreatic cancer cells." (PMID 38110764, 2023). "Conversely, METTL3, a methyltransferase, plays a pro-oncogenic role in pancreatic cancer." (PMID 37063421, 2023). "Furthermore, silencing METTL3 remarkably reduced pancreatic cancer cell proliferation, migration, and invasion both in vitro and in vivo." (PMID 36977668, 2023). "Moreover, METTL3 expressions in pancreatic cancer cell lines were all remarkably rose, which was more remarkable in BxPc-3 cells." (PMID 37936074, 2023). "In the field of pancreatic cancer RNA methylation research, some scientists have illuminated the potential role of the methylation modifying enzyme METTL3 in modulating proliferation, invasion and therapeutic sensitivity, and efforts to investigate the internal mechanism have been made." (PMID 35864471, 2022). "In pancreatic cancer, METTL3-depleted cancer cells showed higher sensitivity to the irradiation." (PMID 35022030, 2022). "In pancreatic cancer, METTL3 knockdown cells are highly sensitive to radiation, so it can be speculated that METTL3 levels will affect radiotherapy." (PMID 35628460, 2022). "The Transwell migration assay also demonstrated that METTL3 could reverse the migration ability of overexpressed/knockdown SMS pancreatic cancer cells." (PMID 36276112, 2022). "The knockdown of METTL3 in pancreatic cancer cell lines increases the sensitivity of the cells to gemcitabine, cisplatin and other drugs, even though the morphology and proliferative abilities of the cells did not change, providing a new potential target for the treatment of pancreatic cancer." (PMID 35155557, 2022). "Moreover, in pancreatic cancer, suppressed METTL3 expression improved the efficacy of anti-cancer agents, such as gemcitabine, 5-fluorouracil, and cisplatin." (PMID 36291060, 2022). "Next, we tested whether METTL3 modulation can govern the expression level of lncRNA MALAT1 in pancreatic cancer cells." (PMID 36212476, 2022). "While the role of METTL3 in promoting proliferation in many cancer types has been well-established, the role of METTL3 in pancreatic cancer proliferation remains controversial as two independent studies found contrasting roles for METTL3 in promoting pancreatic cancer cell proliferation." (PMID 35350378, 2022). "METTL3 expression plays an important role in the TIME of pancreatic cancer." (PMID 36212476, 2022). "METTL3 can promote chemo‐ and radioresistance in human pancreatic cancer." (PMID 35696608, 2022). "We tested how elevated METTL3 expression affects pancreatic cancer in a mouse model." (PMID 35773310, 2022). "We also found that METTL3 controlled the expression of MALAT1 in pancreatic cancer cells." (PMID 36212476, 2022). "Moreover, other evidence suggested that the upregulation of METTL3 can promote proliferation and invasion of pancreatic cancer." (PMID 36212476, 2022).
pancreatic cancer (continued). "In addition, pancreatic cancer was also found to have upregulated METTL3 and downregulated ALKBH5 (m6A eraser) expression, and this dysregulation significantly influenced RNA methylation and resulted in poor clinical outcomes." (PMID 35864471, 2022). "In this study, we provided evidence for a role of NUCB1 in regulating proliferation and the anti-tumor effects of gemcitabine in pancreatic cancer cells, and proposed a mechanism whereby METTL3 controls NUCB1 expression, which then modulates ATF activity and subsequently controls the UPR." (PMID 33855021, 2021). "Moreover, the diminished DNA methylation triggers the enhancement of METTL3, which further induces the maturation of pri-miR-25, promoting the development of pancreatic cancer." (PMID 33754077, 2021). "However, the prognostic value was based on a small patient specimen size, and large-scale patient cohorts from multiple centers are needed to confirm the prognostic role of METTL3 in pancreatic cancer." (PMID 34239358, 2021). "METTL3 expression may induce resistance to chemotherapy as METTL3 knockdown increased sensitivity to gemcitabine, 5-fluorouracil (5-FU) and cisplatin in pancreatic cancer, potentially through activation of MAPK signaling." (PMID 33669361, 2021). "For example, as a “writer,” METTL3 can not only promote the progression of pancreatic cancer by regulating the maturation of miR-25-3P, but it can also promote the tumorigenesis and metastasis of nasopharyngeal carcinoma by enhancing the stability of lncRNA FAM255A." (PMID 34950253, 2021). "Furthermore, METTL3 knockdown decreases m6A modifications and inhibits pancreatic cancer cell proliferation and migration." (PMID 34239358, 2021). "Furthermore, pancreatic cancer patients with lower METTL3, METTL14, RBMX, FTO, ALKBH5, YTHDF1, and YTHDC1 mRNA expression levels or higher VIRMA, HNRNPA2B1, EIF3A, IGF2BP1, IGF2BP2, and IGF2BP3 mRNA expression levels had significantly poorer OS (P < 0.05)." (PMID 34330301, 2021). "Furthermore, pancreatic cancer cells with inhibition of m6A writer METTL3 displays higher sensitivity to cisplatin and gemcitabine." (PMID 34603372, 2021). "In terms of treatment, while METTL3-silenced GSCs and pancreatic cancer cells showed enhanced sensitivity to irradiation, METTL3-depleted cells induced NSCLC and pancreatic cancer chemotherapeutic drug resistance to gemcitabine, 5-fluorouracil, cisplatin, etc.." (PMID 33431045, 2021). "Expression of 28 m6A RNA methylation modulators was extracted from 167 healthy samples from GTEx database and 140 patients with PAAD integrated from TCGA database, All the m6A RNA methylation modulators showed a high expression in pancreatic carcinoma than normal pancreatic tissue except METTL3." (PMID 34332578, 2021). "METTL3 has been found to be highly expressed in pancreatic tumor tissues." (PMID 33372610, 2020). "To elucidate the molecular mechanisms responsible for elevated m6A levels in pancreatic cancer, we assessed the expression of the most important m6A regulatory factors (METTL3, METTL14, and WTAP, which form a complex) in the paired cancer and adjacent tissue samples." (PMID 32843065, 2020). "In addition, METTL3‐depleted pancreatic cancer cells showed higher sensitivity to anticancer reagents such as gemcitabine, 5‐fluorouracil, cisplatin and irradiation, suggesting that METTL3 is a potent target for enhancing therapeutic efficacy." (PMID 33090698, 2020). "Furthermore, depletion of METTL3 increases chemo- and radio-sensitivity in pancreatic cancer therapy." (PMID 32709063, 2020). "In pancreatic cancer, METTL3 correlates with carcinogenesis and may act as a potential therapeutic target." (PMID 33029866, 2020). "Combinatorial treatment of METTL3 inhibitors plus chemo- or radiotherapy may probably display much better outcome in pancreatic cancer patients." (PMID 31921664, 2019). "It has been suggested that METTL3 promotes chemoradiation resistance in pancreatic cancer." (PMID 31757221, 2019).
pancreatic cancer (continued). "Together, our findings first elucidated the detailed molecular mechanism of METTL3 degradation and revealed the pivotal role of the TRIM21-METTL3 axis in regulating ferroptosis and antitumor immunity, which may serve as a potential target for pancreatic cancer treatment." (PMID 40175350, 2025). "Furthermore, we analyzed the protein expression of METTL3 in pancreatic cancer cell lines." (PMID 40175350, 2025). "Additionally, apart from tissue damage in the pathological sections, we finally examined METTL3 protein levels in 88 pairs tissues by immunohistochemistry analysis, and the results revealed increased METTL3-positive staining in pancreatic cancer tissues compared to adjacent normal tissues." (PMID 40175350, 2025). "Therefore, comprehending the molecular mechanisms and downstream targets governed by METTL3 in pancreatic cancer regulation may offer novel avenues for the treatment and diagnosis of this disease." (PMID 40495163, 2025). "However, the therapeutic potential of METTL3 in pancreatic cancer is unclear." (PMID 40495163, 2025). "Besides, we also analyzed the level of METTL3 protein in locally invasive pancreatic cancer tissues compared to controls using Western blot, the results showed that METTL3 protein was significantly highly expressed in pancreatic cancer tissues with localized tissue invasion." (PMID 41285728, 2025). "Furthermore, we found that the supplementation of HMGB1 could alleviate the inhibition of ferroptosis by METTL3 in pancreatic cancer." (PMID 40495163, 2025). "Notably, METTL3 positively regulates the expression of lncRNA MALAT1 in pancreatic cancer cells." (PMID 36212476, 2022). "Increased sensitivity to anticancer reagents including 5-fluorouracil and cisplatin, and irradiation has been observed in METTL3-depleted pancreatic cancer cells, which is consistent with our findings showing that METTL3 knockdown could enhance the sensitivity of AML cells to chemotherapy." (PMID 35761379, 2022). "Moreover, METTL3 positively regulates the expression of PD-L1 in pancreatic cancer cells." (PMID 36212476, 2022). "In addition, to promote tumorigenesis, METTL3 promotes chemotherapy and radiation tolerance, which has been identified as associated with mitogen-activated protein kinase (MAPK) cascades, a ubiquitin-dependent modification in pancreatic cancer." (PMID 34381710, 2021). "Furthermore, METTL3 promotes chemoresistance in pancreatic cancer cells." (PMID 32857912, 2020). "The interplay between Mettl3, Mettl14, miR-380-3p, PTEN, and the AKT pathway sheds light on the regulatory mechanisms involved in pancreatic cancer progression." (PMID 41517663, 2026). "Studies have demonstrated that elevated levels of METTL3 expression are correlated with advanced pathological stages in PDAC, as well as resistance to chemotherapy and radiotherapy in pancreatic cancer cells." (PMID 40495163, 2025). "lncRNA NNT‐AS1 is highly expressed in pancreatic cancer by HIF‐1α‐mediated transcription, and m6A‐modified NNT‐AS1 by METTL3‐HuR stabilizes ITGB1." (PMID 40448344, 2025). "First, we observed that local invasion, METTL3, IGF2BP3 and EMP1 expression levels influence cell infiltration in the pancreatic cancer microenvironment." (PMID 41285728, 2025). "Subsequently, we analyzed the correlation among METTL3 and IGF2BP3 and EMP1 in the pancreatic cancer single-cell dataset." (PMID 41285728, 2025). "Here, we first prove that METTL3 is highly expressed in pancreatic cancer and inhibits ferroptosis-induced gemcitabine resistance, and HMGB1 is identified as a downstream target of METTL3." (PMID 40495163, 2025). "We further explored the role of METTL3, IGF2BP3 and EMP1 in the regulation of the tumor microenvironment in pancreatic cancer." (PMID 41285728, 2025). "Subsequently, infiltration-positive cells were analyzed according to the occurrence of local tissue invasion, METTL3, IGF2BP3 and EMP1 expression levels in pancreatic cancer." (PMID 41285728, 2025).